FBXW7 (F-box and WD repeat domain containing 7)
Diseases named in the same sentence as FBXW7 in open-access papers (continued):
Sharing a sentence is not in itself a finding about the gene and the disease.
tumor (continued). "Interestingly, these findings differ from the well‐established hypothesis that FBXW7 by default acts as a tumor suppressor in several cancers including epithelial tumors." (PMID 33822486, 2021). "FBXW7 regulates the proliferation and differentiation of keratinocytes, and exerts both inhibitory and stimulatory signals during skin carcinogenesis, primarily by counteracting the proliferation‐advancing activity of c‐Myc and the tumor‐suppressive activity of NOTCH." (PMID 33822486, 2021). "An example is FBXW7, a well-known tumor suppressor that may also contribute to tumorigenesis." (PMID 32316282, 2020). "To further determine whether the effect of FBXW7 knockout on M2 macrophage polarization was indeed responsible for tumor progression, we subcutaneously injected wild-type C57BL/6 mice with a mixture of LLCs and FBXW7f/f or Lysm+FBXW7f/f M2-polarized macrophages at a 1:1 ratio." (PMID 33260160, 2020). "FBXW7 depletion in myeloid cells could promote tumor growth." (PMID 33260160, 2020). "Thus, this study showed that by overexpressing FBXW7, its tumor suppressive action may be executed on PC cell through degradation of β-catenin." (PMID 30791487, 2019). "Therefore, we cannot exclude the possibility that Fbxw7 is a weak tumor suppressor, which would be sufficient to drive tumorigenesis with Kras mutation in a small number of mice if we utilized a much larger cohort of mice for the in vivo electroporation experiment." (PMID 31748650, 2019). "Therefore, the downregulation of FBXW7 protein levels may contribute to tumor progression and chemoresistance." (PMID 35582143, 2019). "It has also been elucidated that in bone marrow-derived stromal cells (BMSCs), loss of FBXW7 induced cancer metastasis via upregulation of the chemokine CCL2, which increased the monocytic myeloid-derived suppressor cells (Mo-MDSCs) as well as tumor-associated macrophages (TAMs)." (PMID 30791487, 2019). "Thus, FBXW7 is considered an important tumor suppressor in various cancers." (PMID 29348852, 2017). "Besides, it has been confirmed that FBXW7 is a tumor suppressor and suppresses EMT in HCC cells." (PMID 28716020, 2017). "Due to the inherent complexities of attempting to restore protein function, synthetic lethality provides a feasible strategy to identify vital proteins that cells have become dependent on, in the absence of the FBXW7 tumour suppressor, that can be inhibited to cause selective cancer cell death." (PMID 28829765, 2017). "Thus, Fbxw7 haploinsufficiency is related to the increased tumor incidence in animal experiments." (PMID 28422719, 2017). "Currently, there is no therapy to specifically target FBXW7-deficient tumours." (PMID 28829765, 2017). "However, the function of FBXW7 in tumor metastasis is rarely reported." (PMID 25749036, 2015). "We found no loss of heterozygosity of Fbxw7 in R482Q/+ tumours (n=4)." (PMID 23676439, 2014). "How the decrease in Fbxw7 function results in tumor development remains largely unknown." (PMID 23454868, 2013). "Moreover, in a series of gain-of-function and loss-of-function investigations, we found that these effects may be due to the downregulation of the tumour-suppressor FBXW7, which was targeted by miR-223." (PMID 22108521, 2012).
tumor (continued). "The recent identification of mTOR as a downstream target of Fbxw7 suggests that germline or somatic changes may affect tumor responses to known inhibitors of the mTOR pathway such as rapamycin, and such investigations are presently in progress in this laboratory." (PMID 22348067, 2012). "Fbxw7/hCdc4-β localizes to the cytoplasm and could potentially target a pro-apoptotic substrate(s) or a protein(s) involved in DNA damage signaling that when stabilized sensitize tumor cells to chemotherapeutic drugs." (PMID 21122106, 2010). "Downregulation of FBXW7 leads to the accumulation of these proteins and the consequent activation of the AKT signaling pathway, promoting tumor cell proliferation, survival, and progression." (PMID 41596525, 2026). "M1 and M2 macrophages exerted opposite effects on CRC progression, mediated via the FBXW7-MCL-1 axis, while PI3Kγ inhibition in macrophages influenced EMT and cytotoxicity in tumor cells." (PMID 41373479, 2025). "FBXW7 is a substrate receptor of the SCF E3 ubiquitin ligase and a tumor suppressor, which can enhance the ubiquitination and degradation of oncogene proteins, resulting in inhibition of cancer cell growth, including of UC cells." (PMID 39915362, 2025). "FBXW7 is a tumor suppressor that plays a pivotal role in CRC by regulating the degradation of key oncogenic proteins, influencing tumor initiation, growth, therapeutic response, and metastatic behavior." (PMID 41373479, 2025). "F-box and WD repeat domain-containing 7 (FBW7) is a substrate recognition component of the Skp1-Cul1-F-box (SCF) ubiquitin ligase complex, which can exert tumor inhibition by targeting oncoprotein degradation." (PMID 39769097, 2024). "This can inhibit mitochondrial apoptosis and activate the Wnt/β-catenin pathway by suppressing F-Box and WD repeat domain containing 7 (FBXW7) and modulator of apoptosis 1 (MOAP1), thus promoting the EMT and metastasis of tumor cells." (PMID 39139454, 2024). "Hu and colleagues discovered that miR-92a-3p in CAF-secreted exosomes targets FBXW7 and MOAP1 in tumor cells, enhancing β-catenin expression, tumor stemness, and EMT, while inhibiting apoptosis and leading to metastasis and chemoresistance in CRC." (PMID 39578849, 2024). "For example, E3 ubiquitin ligase FBXW7 inhibits cell proliferation in several cancer cells by ubiquitylating MYC, whereas it promotes cell proliferation in certain tumours by p100 degradation." (PMID 38296968, 2024). "Functional inactivation of FBXW7 led to activation of the MAPK signaling pathway and upregulation of the downstream MMP3 and VEGFA, which enhanced tumor proliferation cell invasion and migration." (PMID 36991467, 2023). "The expression of FBXW7 in the TCGA database was lower, and the expression of MAP4 was higher in tumor tissues compared to adjacent tissues, but the difference was not significant." (PMID 36991467, 2023). "FBXW7 is a crucial component of the SCF ubiquitin ligase complex and acts as a tumor suppressor by regulating the abundance of various oncogenic proteins." (PMID 37408248, 2023). "The F-Box and WD Repeat Domain Containing 7 (FBXW7) protein has been shown to regulate cellular growth and act as a tumor suppressor." (PMID 37408248, 2023). "Taken together, these findings demonstrate that DYRK2 participates in the degradation of multiple FBXW7 substrates and reveals DYRK2 as a general modulator of FBXW7 activity with potential consequences in the damage response and tumor progression." (PMID 36934104, 2023).
tumor (continued). "The mRNA levels of FBXW7 in GSE53622 were significantly decreased, and MAP4 was significantly increased in tumor tissues compared to adjacent tissues." (PMID 36991467, 2023). "Thus FBXW7 may regulate the switching of macrophage phenotype in the tumor microenvironment." (PMID 38027013, 2023). "The enhanced FBXW7 expression inhibits cancer cell proliferation and promotes autophagy in both OSCC cells and xenograft tumor model." (PMID 37249289, 2023). "We studied the effects of FBXW7 overexpression on OSCC cell proliferation and autophagy in cell lines and mouse tumor models." (PMID 37249289, 2023). "FBXW7 promotes ubiquitination and degradation of myeloid leukemia 1 (MCL-1) a member of the pro-survival Bcl-2 family regulating apoptosis in tumor cells." (PMID 35346215, 2022). "FBXW7, a member of the SCF E3 ligase family, functions as a tumor suppressor and contributes to CRPC." (PMID 35612714, 2022). "It is possible that in LMS tumors with high accumulation of DNA damage, disruption of cell cycle checkpoint regulation through RB1, CDKN2A/B, MYC, FBXW7, or NF1 is necessary to maintain the viability of the tumor." (PMID 35468996, 2022). "Then, SEMA3B-AS1 can promote the transcription and expression of FBXW7 through binding HMGB1, thus promoting autophagy and inhibiting apoptosis in tumor cells." (PMID 35273678, 2022). "When we knocked down FBXW7 in the OE-SEMA3B-AS1 group, the tumor suppressive effect of SEMA3B-AS1 was partially attenuated." (PMID 35273678, 2022). "Aberrantly expressed FBXW7 mediates ZMYND8 ubiquitination degradation and enhances tumor progression and stemness in BCa45." (PMID 36147463, 2022). "Thus, we hypothesized that FBXW7 may act as a tumor-suppressive gene in CC." (PMID 35094292, 2022). "Tumor burden and growth kinetics, tumor microenvironment, cell death inhibition, and EMT contribute to therapeutic resistance, which can be leveraged by targeting FBXW7 to elevate therapeutic sensitivity and the prognosis of patients." (PMID 35515121, 2022). "Our previous studies indicated that FBXW7 is markedly downregulated in HCC and is related to tumor migration, invasion, and progression." (PMID 36159747, 2022). "In this study, we enriched the CSCs by inducing tumor sphere formation from HCC cell lines MHCC-97H and Huh7 and measured the mRNA and protein level of FBXW7." (PMID 36159747, 2022). "Downregulation of miR-182-5p contributes to inhibition of cell proliferation and promotion of tumor cell apoptosis by impairing the TLR4/NF-κB signaling pathway activity and increasing FBXW7 expression." (PMID 34294040, 2021). "In contrast, ligases such as FbXW7 or β-TRCP, whose activity leads to the degradation of oncoproteins, are bona fide tumor suppressors." (PMID 34572023, 2021). "The activity of KPT‐185 is strongly correlated to the nuclear retention of FBXW7; which degrades nuclear N1‐ICD, thereby leading to reduced expression of tumor‐promoting markers like Cyclin‐D1, c‐Myc, VEGF, and Hes‐1." (PMID 33822486, 2021). "In this model, LSCC and LADC formation is initiated by KrasG12D activation and Fbxw7 deletion using FLP recombinase, and the Cre-loxP system can then be used for inactivation of Usp28flox/flox in established tumours." (PMID 34636321, 2021). "Major histocompatibility complex (MHC) class I-mediated tumor antigen processing was the hub pathway that was significantly downregulated in lgCMN, and ITCH, FBXW7, HECW2, and WWP1 were identified as candidate hub genes." (PMID 34912899, 2021). "The recruitment of RORA can induce the expression of the tumor suppressor genes F-box/WD repeat-containing protein 7 (FBXW7), Semaphorin 3F (SEMA3F), and P21, leading to apoptosis and suppression of tumor cell proliferation." (PMID 34285836, 2021). "FBW7 (also known as FBXW7, CDC4, AGO, and SEL10) is widely regarded as a tumor suppressor, mainly for its role in mediating degradation of oncoproteins such as c-MYC, Cyclin E, and NOTCH." (PMID 35062263, 2021).
tumor (continued). "However, loss or inactivation of Fbxw7 could have an antitumor or protective effect in Hedgehog-dependent tumors including tumors dependent on inactivating mutations in PTCH1 or activating mutations in SMO, which both require an intact cilium for tumor growth." (PMID 34518642, 2021). "Previous reports have shown that miR-92a-3p has multiple target genes, most of which are tumor suppressors, including PTEN, MYCBP2, FBXW7 and so on." (PMID 34082648, 2021). "Fbxw7 is required for double-stranded RNA sensing and IFN signaling in tumor cells, which in turn is important for promoting antitumor immunity and immunotherapy." (PMID 33436547, 2021). "Accumulated evidence has also revealed that FBXW7 governs the epithelial-to-mesenchymal transition (EMT), stem cell differentiation and drug resistance in tumour cells." (PMID 32655893, 2020). "The F-box/WD repeat-containing protein 7 (FBXW7) is part of the Skp, Cullin, F-box (SCF) complex and is known to be a tumor suppressor." (PMID 32879328, 2020). "In detail, c-Myc and Notch1 have been identified among the target genes through which FBXW7 influences skin carcinogenesis by counteracting the proliferation-promoting effect of c-MYC and the tumor-suppressive effect of NOTCH1, respectively." (PMID 32560247, 2020). "Interestingly, we found an enrichment of cluster 4 in tumour of P1207 without NOTCH1/NOTCH2/FBXW7 mutations, but it is not known whether or not P1207 had mutations in other members of the Notch signalling pathway." (PMID 32924269, 2020). "In a large panel of human cancer cell lines and patient biopsies, FBXW7 abundance was positively correlated with sensitivity to HDAC inhibitors (HDACi), which are known to downregulate ΔNp63 through FBXW7 to induce a tumor-suppressive program." (PMID 32560247, 2020). "Some of these genes, like PTEN, FBXW7, or BIM, have already established tumor suppressive and pro-apoptotic roles, yet their interactions with hsa-miR-20b-5p and hsa-miR-363-3p have not been studied functionally in T-ALL thus far." (PMID 32380791, 2020). "Colony formation in soft agar and tumor growth in nude mice allografts were only detected in MEF-LoxP-KC cells transduced with lentivirus expressing sgRNA targeting either p19Arf, Fbxw7 or Slc9a3." (PMID 31748650, 2019). "Out of the three F-box categories, FBXW, FBXL and FBXO, FBXW7 is a well-established FBXW subfamily protein, which plays a key role as tumor suppressor in the occurrence of many forms of cancers." (PMID 35582143, 2019). "Moreover, simple knockdown of FBXW7 could promote tumor progression." (PMID 31067777, 2019). "On the contrary, circ-FBXW7 overexpression inhibited CRC cells proliferation and migration as well as the growth of tumor weight." (PMID 31519156, 2019). "miR-25 targets directly mRNAs coding for tumor suppressors like FOXO3a, ERBB2, and F-box/WD repeat-containing protein 7 (FBXW7)." (PMID 29967761, 2018).
tumor (continued). "FBXW7 expression is reduced in HCC tissues compared to normal tissue and correlated with tumor differentiation, the incidence of portal or hepatic venous invasion, and metastasis." (PMID 30086763, 2018). "In the case of the PTEN, FBXW7 and SMAD4 genes, as well as several other tumor suppressors, a frequent mechanism of inactivation is through point mutations that reoccur at the defined residues and act dominantly on the molecular level." (PMID 29572294, 2018). "These more frequently mutated instances encompassed in total 53 genes and included the experimentally characterized hotspots within the PTEN, FBXW7, SMAD4, EP300, and CREBBP tumor suppressors." (PMID 29572294, 2018). "In the “waves” pattern CESC, the first wave genes EP300, MLL2, and MLL3 were all tumor suppressor genes, and the second wave genes FBXW7 and ATRX were also tumor suppressor genes." (PMID 26992457, 2016). "IHC analysis of the tumor specimens exhibited a significant loss of E-cadherin expression in metastatic IHCC and PHCC and a positive correlation between the expression of FBXW7 and E-cadherin in IHCC and PHCC, indicating FBXW7 may be involved in the EMT of CCA." (PMID 25749036, 2015). "We found that the expression of FBXW7 was lower in both CCA cell lines and tumor tissues compared with normal intrahepatic bile duct epithelial cells and tumor adjacent tissues respectively." (PMID 25749036, 2015). "The Fbxw7 and YAP expression in 60 samples of surgical resected HCC and matched normal tumor-adjacent tissues were assessed using IHC or immunoblotting." (PMID 24884509, 2014). "miR-223 was found promoted the growth and invasion of tumor cells by targeting tumor suppressor PAX6 and FBXW7/hCdc4." (PMID 25329674, 2014). "Many F-box proteins such as FBXW7, FBXL2, FBX4 and FBXO11 are found to be lost in a wide range of human cancers, and generally considered as tumor suppressor genes." (PMID 23826080, 2013). "FBXW7, a component of the SCF (Skp1/Cullin/F-box protein) E3 ubiquitin ligase complex, acts as a tumor suppressor in several tissues and targets multiple transcriptional activators and proto-oncogenes for ubiquitin-mediated degradation." (PMID 22879877, 2012). "The inactivation of FBXW7 may enhance the WNT/β‐catenin pathway, which is known to play a crucial role in tumor progression by promoting cell proliferation and survival." (PMID 41522471, 2026). "Given that FBXW7 is a negative regulator of tumor growth and RPAP2, a novel FBXW7 substrate, is required for the growth and survival of HCC cells, we investigated whether RPAP2 accumulation plays a causal role in the tumor growth induced by FBXW7 knockdown." (PMID 39932049, 2025). "Thus, FBXW7 status not only influences cancer cell–intrinsic immunogenic features but also helps shape the surrounding TIM, underscoring its dual role in tumor progression and immunotherapy responsiveness." (PMID 41373479, 2025). "USP28 loss in FBXW7-deficient mice slows proliferation, restores differentiation, and partially reverses tumorigenesis, showing USP28 promotes tumor growth without FBXW7." (PMID 41373479, 2025). "Furthermore, ENKUR also binds to E3 ligase F-box and WD repeat domain containing 7 (FBXW7), a critical tumor suppressor." (PMID 39990660, 2025). "In recent published in vivo studies, FBXW7 and KEAP1 were suggested to confer immune checkpoint blockade by alternating tumor microenvironment instead of directly modifying the tumor, through the way of decreasing T-cell infiltration and downregulating IFN-γ signaling, respectively." (PMID 41195266, 2025). "Unexpectedly, we did not observe significant tumor development in the livers of Fbxw7 null mice for up to 15 months." (PMID 39932049, 2025). "To date, a genome‐wide assessment of candidate targets in FBXW7 defective tumour cells has not been made." (PMID 37866880, 2024).